VIP (vasoactive intestinal peptide)
Description:
[Vasoactive intestinal peptide]: VIP is a neuropeptide involved in a diverse array of physiological processes through activating the PACAP subfamily of class B1 G protein-coupled receptors: VIP receptor 1 (VPR1) and VIP receptor 2 (VPR2). Abundantly expressed throughout the CNS and peripheral nervous systems where they primarily exert neuroprotective and immune modulatory roles. Also causes vasodilation, lowers arterial blood pressure, stimulates myocardial contractility, increases glycogenolysis and relaxes the smooth muscle of trachea, stomach and gall bladder. [Intestinal peptide PHM-27]: Bioactive forms that cause vasodilation. PHM-27 is a potent agonist of the calcitonin receptor CALCR, with similar efficacy as calcitonin. [Intestinal peptide PHV-42]: Bioactive forms that cause vasodilation.
Synonyms: PHM27
Tractability: Antibody: its Gene Ontology location is reachable by antibodies, with high confidence; UniProt places it where antibodies can reach, with medium confidence; UniProt predicts a signal peptide or a membrane-spanning region.
Target class: Secreted protein
Gene: Protein-coding gene on chromosome 6 (152,749,922 to 152,759,765, forward strand). Ensembl gene ENSG00000146469.
Subcellular location: Secreted
Subcellular location (Human Protein Atlas): Endoplasmic reticulum; Predicted to be secreted
Pathways (Reactome):
Signal Transduction: G alpha (s) signalling events; Glucagon-type ligand receptors
Gene Ontology:
Molecular function: hormone activity; neuropeptide hormone activity; peptide hormone receptor binding; protein binding; type 1 vasoactive intestinal polypeptide receptor binding; type 2 vasoactive intestinal polypeptide receptor binding; signaling receptor binding
Biological process: adenylate cyclase-activating G protein-coupled receptor signaling pathway; positive regulation of protein catabolic process; regulation of protein localization; body fluid secretion; epinephrine secretion; G protein-coupled receptor signaling pathway; mRNA stabilization; positive regulation of cAMP/PKA signal transduction; positive regulation of cell population proliferation; prolactin secretion
Cellular component: extracellular region; neuron projection
Genetic constraint (gnomAD): Loss-of-function variants: 15 observed, 15.7 expected, observed/expected ratio (o/e) 0.96, 90% interval 0.64 to 1.47. The upper end of that interval is the gene's LOEUF score, 1.47, which puts it in group 6 of 6, group 1 being the genes least tolerant of losing a copy. Missense variants: 161 observed, 170.29 expected, observed/expected ratio (o/e) 0.95, 90% interval 0.83 to 1.08. Synonymous variants: 64 observed, 61.08 expected, observed/expected ratio (o/e) 1.05, 90% interval 0.86 to 1.29.
Homologues: Orthologues: chimpanzee VIP (99% identical), macaque VIP (97% identical), dog VIP (86% identical), pig VIP (82% identical), rabbit VIP (82% identical), rat Vip (82% identical), mouse Vip (79% identical), guinea pig VIP (71% identical), tropical clawed frog vip (61% identical), zebrafish vip (45% identical), zebrafish vipb (44% identical). Paralogues in human: ADCYAP1 (29% identical), GHRH (19% identical).
Diseases named in the same sentence as VIP in open-access papers:
VIP is named in the same sentence as 372 diseases in open-access papers, as found by Europe PMC text mining. Sharing a sentence is not in itself a finding about the gene and the disease. The quoted sentences say what the papers report.
migraine (80 papers, 2009 to 2025). "PACAP shares homology with vasoactive intestinal polypeptide (VIP) and is one of several vasoactive neuropeptides along with CGRP and VIP, which has been implicated in migraine neurobiology." (PMID 38887982, 2024). "Future research is required to unveil the mechanisms underlying VIP-induced migraine attacks and the potential utility of VIP as a possible biomarker." (PMID 36982428, 2023). "For example, a randomized clinical trial found that a 2-h infusion of VIP caused migraine episodes, suggesting an important role of VIP in migraine pathophysiology." (PMID 37998384, 2023). "In the case of PACAP, the family member vasoactive intestinal peptide (VIP) caused migraine-like headaches comparable to PACAP, but only after prolonged infusion to mimic the longer lasting vascular actions of PACAP." (PMID 37009867, 2023). "Nonetheless, recent provocation data have found that intravenous infusion of VIP over 120 min (instead of 20 min) causes headache and arterial dilation for > 2 h in healthy volunteers and migraine attacks in 15 (71%) of 21 participants with migraine." (PMID 35870898, 2022). "The underlying pathogenic mechanisms used by PACAP and VIP to induce migraine-like attacks are unclear." (PMID 36430275, 2022). "A 2-hour infusion of VIP caused migraine attacks, suggesting an important role of VIP in migraine pathophysiology." (PMID 34357396, 2021). "PACAP-38 and VIP are both described as parasympathetic vasodilator peptides, and they are linked to cranial autonomic symptoms in migraine and TACs." (PMID 29536279, 2018). "VIP has also been implicated in the pathophysiology of migraine." (PMID 37998384, 2023). "In animal models, stimulation of the superior sagittal sinus as an experimental migraine model causes raised external jugular VIP levels, and locus coeruleus stimulation could increase cranial blood flow by a mechanism antagonised by VIP polyclonal antibodies." (PMID 37569369, 2023). "Future studies will improve our understanding mechanisms underlying VIP-induced migraine attacks." (PMID 35432170, 2022). "Can vasoactive intestinal polypeptide (VIP) cause migraine attacks?" (PMID 34357396, 2021). "Therefore, it remains unclear whether differences in VIP expression are the cause or effect of migraine chronification; further research is required to elucidate the molecular mechanisms involved in migraine chronification or transformation." (PMID 38612517, 2024). "Furthermore, VIP is implicated in the physiological and pathophysiological roles of migraine." (PMID 37998384, 2023). "The recent demonstration that VIP can, in fact, trigger migraine in those with underlying migraine, as well as other migraine-related behaviours in animal models, suggests that the VPAC1 and VPAC2 receptors may also hold therapeutic potential as migraine targets for the future." (PMID 37569369, 2023). "Furthermore, PACAP infusion caused an increase in plasma levels of VIP in people with migraine." (PMID 37143998, 2023). "However, more recently, a model of prolonged infusion of VIP (e.g., 2 h) has been proven to cause long-lasting dilation of the superficial temporal artery and delayed headache in both healthy volunteers and patients with migraine." (PMID 37569648, 2023). "At present, the mechanisms underlying VIP-induced migraine remain unknown." (PMID 35432170, 2022). "For example, vasoactive intestinal polypeptide (VIP) demonstrated migraine-inducing properties only after prolonged infusion." (PMID 40260134, 2025). "VIP liberation is increased in migraine patients during attacks; moreover, NO release is functionally coupled to VIP secretion under certain conditions, and it can increase the levels of NO, too." (PMID 40003563, 2025). "More recently, a prolonged VIP infusion has been shown to provoke migraine attacks in 71% in one study (compared to 5% with placebo), and VIP infusion was associated with prolonged extracranial vasodilatation." (PMID 38887982, 2024).
migraine (continued). "Some neuropeptides and neurotransmitters are implicated in promoting the risk of migraine occurrence in GERD, including calcitonin gene-related peptide (CGRP), vasoactive intestinal peptide (VIP), and serotonin." (PMID 38990854, 2024). "But the human model has delivered many other migraine‐provoking molecules such as vasoactive intestinal polypeptide (VIP), phosphodiesterase‐5 (PDE5) inhibitor sildenafil, PDE3 inhibitor cilostazol, histamine, prostanoids and potassium channel openers." (PMID 38894592, 2024). "PACAP, a member of the vasoactive intestinal peptide (VIP) family, has been shown to play a role in migraine." (PMID 38671969, 2024). "There is a pressing need for more research to craft alternative targeted migraine therapies, such as those focusing on VIP, amylin, adrenomedullin, PDE3, PDE5, calcium channels, and ASICs." (PMID 37755358, 2023). "Activation of the trigeminal vascular system and trigeminal autonomic reflex, as demonstrated by an increase in CGRP and VIP during attacks, are well-established mechanisms involved in pathophysiology of CH and migraine." (PMID 36832077, 2023). "VIP levels have been shown to be elevated in interictal episodic and chronic migraine patients and to correlate with clinical CAS associated with migraine." (PMID 37569369, 2023). "A more recent study reported that a two-hour infusion of VIP induced migraine attacks in 71% of patients with a history of migraine without aura." (PMID 37370051, 2023). "An increase in VIP plasma levels was reported in animal models of migraine based on the electrical stimulation of the trigeminal ganglion or dura mater." (PMID 36982428, 2023). "Among the complex scenarios of the trigeminovascular activation in the migraine attack, VIP seems to play an important role along with its homologous peptide PACAP." (PMID 37370051, 2023). "Using a double-blind, crossover design, a head-to-head comparison study of PACAP38 and VIP reported a significantly higher migraine-induction rate after PACAP38 compared to VIP (73% vs 18%, respectively)." (PMID 37370051, 2023). "The importance of further research into the roles of PACAP and VIP in migraine pathophysiology is emphasized, along with the development of targeted therapies." (PMID 37998384, 2023). "Further research is needed to develop alternative targeted therapies to prevent migraine (i.e. targeting VIP, amylin, adrenomedullin, PDE3, PDE5, calcium channels, and ASICs)." (PMID 37370051, 2023). "This review paper aims to provide insights into the roles of PACAP in migraine by comparing its actions with those of VIP." (PMID 37998384, 2023). "The differences in symptomatic manifestation observed in preclinical studies of CGRP, PACAP, and VIP are most likely due to their distinct roles in migraine physiology and pathophysiology." (PMID 37998384, 2023). "The neuropeptide VIP, found in the trigeminal nerve, plays a key role in the progression of migraines development." (PMID 37998384, 2023). "Serum VIP is elevated not only during migraine attacks but also during interictal periods of episodic and chronic migraines." (PMID 37373239, 2023). "This suggests that the long-lasting (probably vascular) effect of VIP is more important for migraine induction." (PMID 37370051, 2023). "It explores the similarities between PACAP and VIP, which are involved in sleep regulation and circadian rhythm, suggesting their key roles in migraines." (PMID 37998384, 2023). "By updating our knowledge of PACAP and its unique contribution to migraine pathophysiology, we can pave the way for reinforcing PACAP and other secretin peptides, including VIP, as a novel treatment option for migraines." (PMID 37998384, 2023). "Increased plasma levels of CGRP were found in EM before the onset of migraine attacks but were unrelated to the occurrence of VIP-triggered migraine attacks." (PMID 36982428, 2023).
migraine (continued). "Future studies with predefined outcomes and larger sample size will help to clarify the role of CGRP in VIP induced migraine." (PMID 35432170, 2022). "An additional argument was based on the observation that while some vasodilators like nitroglycerin induce headache in migraine patients, another dilator, vasoactive intestinal peptide failed." (PMID 35432179, 2022). "Other studies have brought to evidence that the use of sumatriptan reduce the salivary VIP level, which is elevated in interictal phase in patients with migraine." (PMID 35328439, 2022). "The major finding of this study is that a 2-h infusion of VIP elevated plasma levels of CGRP in patients with migraine." (PMID 35432170, 2022). "In one randomized, double-blind, 2-way crossover study, participants with migraine were allocated to receive intravenous infusion with PACAP or VIP over 20 min on two separate experimental days." (PMID 35870898, 2022). "VIP has been shown to induce headaches, and sustained VIP infusion can induce delayed migraine-like symptoms in migraine patients." (PMID 36430275, 2022). "A double-blind, crossover study demonstrated that VIP induced migraine attacks in a large proportion of patients with migraine." (PMID 35432170, 2022). "The present study showed elevated plasma levels of CGRP during a 2-h infusion of VIP in patients with migraine." (PMID 35432170, 2022). "A 20-minute infusion of PACAP induced delayed migraine attacks in migraine patients 4-5 hours after the termination of the infusion while two hours of continuous VIP infusion was necessary to generate migraine attacks." (PMID 36387999, 2022). "Given the exploratory design of our study, further investigations are needed to clarify the role of CGRP in VIP-induced migraine." (PMID 35432170, 2022). "The activation of perivascular fibers and the consequent release of vasoactive peptides, including the vasoactive intestinal polypeptide (VIP), play a role in migraine pathogenesis." (PMID 35432170, 2022). "For example, some authors showed how rizatriptan administration leads to a significant reduction of VIP levels measured in external jugular venous blood during spontaneous migraine attacks." (PMID 35328439, 2022). "Previously, one study reported elevated plasma levels of CGRP and VIP in two patients with migraine with aura during the headache phase and prominent symptoms of lacrimation and rhinorrhea." (PMID 35432170, 2022). "Two hours infusion of VIP was necessary to trigger migraine attacks and the period of vasodilation was shorter." (PMID 36387999, 2022). "Several sensory neuropeptides involved in neurovascular control and inflammation have been associated with migraine pathology including CGRP, PACAP, and VIP." (PMID 36387999, 2022). "More recently, sustained infusion of VIP reportedly produced delayed headache and migraine-like symptoms." (PMID 36430275, 2022). "Some studies have shown the influence of some drugs used in the treatment of migraine, in particular triptans, on the VIP levels and consequently their effectiveness in the reduction of pain in migraine." (PMID 35328439, 2022). "Recently, we proposed that VIP induces migraine through the vasoactive intestinal polypeptide receptor 1 (VPAC1) and the vasoactive intestinal polypeptide receptor 2 (VPAC2)." (PMID 35432170, 2022). "Vasoactive intestinal polypeptide (VIP) and pituitary adenylate cyclase-activating polypeptides (PACAPs) are structurally and functionally related, yet different in their migraine-inducing properties." (PMID 34357396, 2021). "Although VIP plasma levels were shown to increase after migraine attacks and/or interictal period in both EM or CM, its infusion did not induce migraine attack." (PMID 35002925, 2021). "The primary end point was the difference in incidence of experimentally induced migraine attacks during the observational period (0-12 hours) between VIP and placebo." (PMID 34357396, 2021).
migraine (continued). "Vasodilation of blood vessels to the brain has been shown to be augmented in the period of intense migraines, and levels of VIP and nitric oxide (NO) (neurotransmitters involved with vasodilation) are upregulated." (PMID 33653014, 2021). "Studies that conducted on people with migraine indicated that serum VIP level was elevated in CM patients with increased cranial parasympathetic system activity during migraine attacks and also in the interictal period in both episodic and CM." (PMID 35002925, 2021). "In this study, CGRP, PACAP, NPY, VIP, and nociceptin were recorded at different times after stimulation to explore the dynamic changes in the neuropeptides during migraine attacks." (PMID 34963819, 2021). "Concentrations of PACAP-38 and VIP were significantly higher in migraine patients than healthy individuals." (PMID 33653014, 2021). "The sum of the peak areas of the endogenously cleaved peptides from the prohormone VIP were significantly different between the control and treatment groups of migraine and OIH in the NAc region." (PMID 31649062, 2019). "In another MRA study, PACAP infusion induced headache in 91% of included migraine patients, and 73% reported migraine-like attacks compared to 82% and 18%, respectively, after VIP administration." (PMID 30088106, 2018). "There are increased levels of PACAP and VIP in the extracranial vasculature during both spontaneous migraine and cluster headache, although VIP levels during severe migraine are only increased when accompanied by cranial autonomic symptoms." (PMID 29536279, 2018). "More recently, the triptan effect was examined after the experimental administration of vasoactive neuropeptides such as CGRP, PACAP-38 and VIP, in healthy volunteers and migraine patients." (PMID 29019093, 2017). "In some attacks of migraine and in most attacks of CH, there is a release of vasoactive intestinal peptide (VIP) originating from parasympathetic cranial ganglia such as the sphenopalatine ganglion (SPG)." (PMID 27587062, 2016). "The biological role of VIP in migraine is also extremely complex." (PMID 41473187, 2025). "Three neurochemicals are most closely associated with migraine: serotonin, CGRP, and γ-amino butyric acid (GABA) but several other pathways including Poly-Adenylate Cyclase Activating Peptide (PACAP) and Vasoactive Intestinal Peptide (VIP) are also involved." (PMID 40823308, 2025). "In a study of long-lasting infusion migraine was provoked by VIP." (PMID 38902612, 2024). "VIP involvement in migraine chronification has been suggested." (PMID 38612517, 2024). "In a rat model of migraine, using unilateral sympathectomy, VIP could reduce sympathectomy-induced raised dural NO levels." (PMID 37569369, 2023). "On the other hand, provocation studies with a 20 min infusion of VIP resulted in a short-lasting dilation of the superficial temporal and middle meningeal arteries in the absence of headache, in both healthy controls and patients with migraine." (PMID 37569648, 2023). "VIP and PACAP-induced vasodilation were partially blocked by PG 97-269, indicating that PACAP and VIP may play a role in migraine pathophysiology and that PG 97-269 may have therapeutic potential for migraine." (PMID 37998384, 2023). "Targeting VIP signaling pathways may therefore represent a promising approach for the development of novel therapies for chronic pain or migraine." (PMID 37998384, 2023). "In preclinical studies, VIP has been shown to change the activity of nociceptive neurons in the trigeminal ganglion and make the TNC more sensitive, which can cause chronic pain or migraines." (PMID 37998384, 2023). "The PAC1 receptor is more specific to PACAP and has therefore had the most interest in migraine, particularly given initial suggestions that VIP was not implicated in the pain part of migraine." (PMID 37569369, 2023).